MIR361 (microRNA 361)
Synonyms: hsa-mir-361; MIRN361; mir-361
Gene: MicroRNA gene on chromosome X (85,903,636 to 85,903,707, reverse strand). Ensembl gene ENSG00000199051.
Gene Ontology:
Biological process: miRNA-mediated post-transcriptional gene silencing
Cellular component: RISC complex
Homologues: Orthologues: chimpanzee ptr-mir-361 (100% identical), macaque mml-mir-361 (100% identical), guinea pig MIR361 (94% identical), pig ssc-mir-361 (92% identical), mouse Mir361 (90% identical), dog MIR361 (85% identical), rabbit MIR361 (85% identical).
Diseases named in the same sentence as MIR361 in open-access papers:
MIR361 is named in the same sentence as 1 disease in open-access papers, as found by Europe PMC text mining. Sharing a sentence is not in itself a finding about the gene and the disease. The quoted sentences say what the papers report.
tumor (1 paper, 2017). "Among these miRNAs, Mir107 and Mir361 have been reported to suppress tumor growth and stem cell growth." (PMID 28725177, 2017).